TMEM147 (transmembrane protein 147)
Description:
Component of the multi-pass translocon (MPT) complex that mediates insertion of multi-pass membrane proteins into the lipid bilayer of membranes. The MPT complex takes over after the SEC61 complex: following membrane insertion of the first few transmembrane segments of proteins by the SEC61 complex, the MPT complex occludes the lateral gate of the SEC61 complex to promote insertion of subsequent transmembrane regions. Also acts as a negative regulator of CHRM3 function, most likely by interfering with its trafficking to the cell membrane. Negatively regulates CHRM3-mediated calcium mobilization and activation of RPS6KA1/p90RSK activity. Regulates LBR localization to the nucleus inner membrane.
Synonyms: NIFIE14; MGC1936; NEDFLPH
Tractability: Antibody: UniProt places it where antibodies can reach, with medium confidence; UniProt predicts a signal peptide or a membrane-spanning region; its Gene Ontology location is reachable by antibodies, with medium confidence. PROTAC: ubiquitination databases record sites on it; its protein half-life has been measured.
Gene: Protein-coding gene on chromosome 19 (35,545,600 to 35,547,527, forward strand). Ensembl gene ENSG00000105677.
Subcellular location: Endoplasmic reticulum membrane; Nucleus membrane; Cell membrane
Gene Ontology:
Molecular function: protein binding; ribosome binding
Biological process: multi-pass transmembrane protein insertion into ER membrane; protein localization to nuclear inner membrane
Cellular component: endoplasmic reticulum membrane; multi-pass translocon complex; nuclear membrane; protein-containing complex; plasma membrane
Genetic constraint (gnomAD): Loss-of-function variants: 29 observed, 31.01 expected, observed/expected ratio (o/e) 0.94, 90% interval 0.69 to 1.27. The upper end of that interval is the gene's LOEUF score, 1.27, which puts it in group 5 of 6, group 1 being the genes least tolerant of losing a copy. Missense variants: 260 observed, 304.82 expected, observed/expected ratio (o/e) 0.85, 90% interval 0.77 to 0.94. Synonymous variants: 121 observed, 117.87 expected, observed/expected ratio (o/e) 1.03, 90% interval 0.88 to 1.19.
Homologues: Orthologues: chimpanzee TMEM147 (99% identical), dog TMEM147 (99% identical), pig TMEM147 (99% identical), rat Tmem147 (99% identical), mouse Tmem147 (99% identical), guinea pig TMEM147 (98% identical), macaque TMEM147 (82% identical), zebrafish tmem147 (78% identical), tropical clawed frog tmem147 (78% identical), Drosophila melanogaster CG5861 (48% identical), Caenorhabditis elegans ZK418.5 (41% identical).
Diseases named in the same sentence as TMEM147 in open-access papers:
TMEM147 is named in the same sentence as 13 diseases in open-access papers, as found by Europe PMC text mining. Sharing a sentence is not in itself a finding about the gene and the disease. The quoted sentences say what the papers report.
hepatocellular carcinoma (7 papers, 2023 to 2026). A malignant tumor that arises from hepatocytes. "For instance, the overexpression of transmembrane protein 147 (TMEM147) was observed in patients with hepatocellular carcinoma, and elevated TMEM147 expression was linked to poor prognosis." (PMID 38460946, 2024). "One such protein, transmembrane protein 147 (TMEM147), has recently been implicated for its role in hepatocellular carcinoma (HCC) tumorigenesis; however, the mechanisms remain unclear." (PMID 37891677, 2023). "BOS complex subunit transmembrane protein 147 (TMEM147) is upregulated in hepatocellular carcinoma (HCC) cells." (PMID 40270603, 2025). "Transmembrane protein 147 (TMEM147) upregulates DHCR7 via signal transducer and activator of transcription 2 (STAT2) in hepatocellular carcinoma (HCC), elevating 27HC and GPX4, which strengthens ferroptosis resistance and metastasis." (PMID 41596341, 2026). "In a hepatocellular carcinoma (HCC) study, researchers demonstrated that CSPG4P12, combining 5 other genes (BX537318.1, TMEM147, AC015908.3, CEBPZOS, and SRD5A3), served as the signature for prognostic evaluation of HCC." (PMID 38877481, 2024).
colon cancer (6 papers, 2016 to 2023). "Transmembrane protein 147 (TMEM147) has been implicated in the development of colon cancer." (PMID 37335919, 2023). "Silencing of TMEM147 in H508 colon cancer cells, where TMEM147 and the M3R are normally co-expressed, causes an increase in the receptor molecules on the cell surface along with an overall increase in the properly folded receptors, implicating TMEM147 in both trafficking and folding of M3R." (PMID 34638576, 2021). "A recent study reported that high expression of TMEM147 may contribute to the development of colon cancer." (PMID 37305689, 2023). "Consistent with our findings, TMEM147 levels in colon cancer were considerably higher than those in controls, which suggested that it could serve as a biomarker for the disease." (PMID 37891677, 2023). "Research has revealed that colon cancer exhibits high mRNA expression of TMEM147, which could thus be involved in the pathogenesis of colon cancer." (PMID 37305689, 2023). "Another functional illustration revealed that TMEM147 adversely controlled calcium mobilization caused by the cholinergic receptor muscarinic 3 (CHRM3) and interfered with its trafficking to the cell membrane in colon cancer." (PMID 37305689, 2023). "In colon cancer, the TMEM147 expression was significantly increased and might represent a biomarker." (PMID 35991561, 2022).
Intellectual disability (2 papers, 2020 to 2022). "Our findings provide clinical, genetic, and functional evidence that bi-allelic loss-of-function variants in TMEM147 cause syndromic intellectual disability due to ER-translocon and nuclear organization dysfunction." (PMID 36044892, 2022). "Similarly, a mutation in TMEM147 has been linked to a rare neurodevelopmental disorder manifesting with severe intellectual disability and impaired vision." (PMID 32820719, 2020). "Overall, TMEM147 should be considered as a gene responsible for intellectual disability, developmental delay, and facial dysmorphism and should be considered as a potential differential diagnosis with chromatinopathies or RASopathies." (PMID 36044892, 2022).
osteosarcoma (2 papers, 2022 to 2023). A usually aggressive malignant bone-forming mesenchymal neoplasm, predominantly affecting adolescents and young adults. "Similarly, in osteosarcoma, the prognostic marker TMEM147 has been linked to immune cell infiltration and the immunological microenvironment." (PMID 37305689, 2023). "According to earlier research, osteosarcomas with higher TMEM147 expression have less M2 macrophage infiltration and a worse prognosis." (PMID 37305689, 2023). "Here, we found that the expression of TMEM147 negatively correlated with the prognosis of osteosarcoma patients in the TCGA cohort." (PMID 35991561, 2022). "The role of TMEM147 deserved further investigation and it might be a novel therapeutic target in osteosarcoma." (PMID 35991561, 2022). "In addition to macrophages, neutrophils, DCs, and T cells had significantly different abundances in osteosarcomas with high and low TMEM147 expression, indicating that TMEM147 may mediate the immune microenvironment in osteosarcomas." (PMID 37305689, 2023). "Prognosis-related TMEM protein family genes were identified by the univariate Cox regression analysis and were utilized to construct a signature based on six TMEM protein family genes (TMEM120B, TMEM147, TMEM9B, TMEM8A, TMEM59, and TMEM39B) in osteosarcoma." (PMID 35991561, 2022).
colorectal cancer (1 paper, 2015). A primary or metastatic malignant neoplasm that affects the colon or rectum. "TMEM147 stimulates cell proliferation in colorectal cancer through negative regulation of the M3 muscarinic receptor expression." (PMID 26056045, 2015).
glioma (1 paper, 2024). A benign or malignant brain and spinal cord tumor that arises from glial cells (astrocytes, oligodendrocytes, ependymal cells). "Similarly, DAB2IP knockdown led to increased RELB binding to TMEM147, which is known to regulate cell proliferation, and PSENEN, a prognostic marker in low-grade gliomas." (PMID 39418101, 2024).
liver cancer (1 paper, 2023). An epithelial or non-epithelial malignant neoplasm that arises from the liver. "It was found that TMEM147 was mainly expressed in macrophages, and its expression in macrophages was lower in liver cancer tissues compared with the adjacent normal tissues." (PMID 37335919, 2023).
prostate carcinoma (1 paper, 2022). A carcinoma that arises from epithelial cells of the prostate gland. "Studies have shown that TMEM147 interacts with the lamin B receptor in the endoplasmic reticulum, affecting the expression level and localization of the receptor, and TMEM147 can also promote the proliferation of prostate cancer." (PMID 37305349, 2022).
rheumatoid arthritis (1 paper, 2023). A chronic, systemic autoimmune disorder characterized by inflammation in the synovial membranes and articular surfaces. "Downregulation of TMEM147 suppresses cytokine-induced rheumatoid arthritis (RA) by inhibiting the activation of nuclear factor kappa B signaling." (PMID 37305689, 2023).
tumor (7 papers, 2022 to 2025). "Second, we conducted diagnostic analysis in all HCC patients from TCGA database, thus the diagnostic value of TMEM147 in different tumor stages, especially in early stages, remains undetermined and warrants further study." (PMID 37335919, 2023). "Considering that GSEA showed that there may be an association between TMEM147 and tumor immunity, ssGSEA was used to test whether TMEM147 expression correlates with immune infiltration in HCC." (PMID 37305689, 2023). "Conversely, Psenen, Tbcb, and Tmem147 are three of the top downregulated DEGs that were highly expressed in control tumor cells but were drastically reduced across Ascl1-OE tumor cells." (PMID 39609428, 2024). "It was found that the TMEM147 mRNA level was positively correlated with individual cancer stages and tumor grade." (PMID 37335919, 2023). "Collectively, these results indicate that elevated TMEM147 protein level in HCC boosts tumor cell proliferation and metastases." (PMID 37891677, 2023). "We further explored the expression of TMEM147 in different subgroups stratified by tumor stage, tumor grade, nodal metastasis status, and other clinical pathological features." (PMID 37335919, 2023). "Multivariate Cox analysis showed that pathological stage (Stage III & IV vs. Stage I & II), tumor status (with tumor vs. tumor free), and TMEM147 expression (high) were independent prognostic factors for OS." (PMID 37305689, 2023). "Real time quantitative PCR (RT-qPCR) and Western blot analysis of tumor tissues and cell lines were used to verify TMEM147 expression in HCC." (PMID 37305689, 2023). "Four prognostic factors, namely, T stage, N stage, tumor status, and TMEM147 expression, were integrated into the TCGA data analysis." (PMID 37305689, 2023). "HCC patients were further subdivided according to individual cancer stage, tumor grade, and patient’s gender, then the prognostic value of TMEM147 in these subgroups was analyzed." (PMID 37335919, 2023). "Moreover, we revealed that high TMEM147 expression was associated with shorter survival times and that TMEM147 could be a risk factor for overall survival, along with T stage, M stage, pathological stage, and tumor status." (PMID 37305689, 2023). "In parallel, we constructed a prognostic nomogram based on T and N classification, tumor status, and TMEM147 expression in HCC." (PMID 37305689, 2023). "Emerging evidence reveals the vital roles of TMEM147 in tumor occurrence and progression." (PMID 37305689, 2023). "Furthermore, TMEM147 promoted tumor immune infiltration, and macrophages were the immune cells that predominantly expressed TMEM147 in HCC." (PMID 37335919, 2023). "TMEM147 promoted tumor cell proliferation and metastases in vitro and in vivo." (PMID 37891677, 2023). "Finally, the associations between TMEM147 expression in HCC and tumor immune cell infiltration were investigated to evaluate the underlying mechanisms of TMEM147." (PMID 37305689, 2023). "Based on these findings, TMEM147 may play a key role in immune regulation and contribute to tumor progression." (PMID 37305689, 2023). "However, 27HC supplementation neutralized the inhibition of lung metastasis by DHCR7 knockdown, whereas the injection of the CYP27A1 inhibitor GW297X in cells overexpressing TMEM147 restrained tumor progression and metastasis, and supplementation with 27HC offset the effect of GW297X." (PMID 37891677, 2023). "Therefore, a reasonable speculation is that TMEM147 promotes tumor progression possibly by affecting protein biosynthesis in HCC." (PMID 37335919, 2023). "In this study, we firstly demonstrated that TMEM147 was overexpressed in HCC and positively correlated with cancer stage and tumor grade." (PMID 37335919, 2023). "In parallel with our observation in vitro, tumor size and weight in the erastin group were significantly increased by TMEM147 overexpression, whereas GW297X pretreatment markedly reversed this TMEM147-mediated oncogenic effect." (PMID 37891677, 2023).
cancer (6 papers, 2021 to 2024). A tumor composed of atypical neoplastic, often pleomorphic cells that invade other tissues. "We used the Wilcoxon rank-sum test to compare the expression of TMEM147 among multiple cancer types according to TCGA data." (PMID 37305689, 2023). "TMEM147 was widely expressed in multiple types of cancer and was overexpressed in the vast majority of cancer types including HCC." (PMID 37335919, 2023). "The difference in the level of TMEM147 mRNA expression between various cancer tissues and normal tissues was assessed using TIMER based on TCGA data." (PMID 37335919, 2023). "TMEM147 expression was significantly higher in 25 types of cancer, including HCC, than in the corresponding normal tissues." (PMID 37305689, 2023). "Similarly, TMEM147 and TMEM41B are transmembrane proteins associated with the pathogenesis of various cancers." (PMID 38365771, 2024). "Our results indicate that TMEM147 confers ferroptosis resistance and M2 macrophage polarization, which are primarily dependent on the upregulation of cellular cholesterol homeostasis and 27HC secretion, leading to cancer growth and metastasis." (PMID 37891677, 2023). "For instance, it is tantalizing to speculate in how far TMEM147 expression may be therapeutic in cancer by limiting RTN4 action." (PMID 34638576, 2021).
neurodevelopmental disorder (2 papers, 2020 to 2022). A behavioral and cognitive disorder with onset during the developmental period that involves impaired or aberrant development of intellectual, motor, or social functions. "We discovered that individuals with bi-allelic TMEM147 loss-of-function variants show a neurodevelopmental disorder associated with facial dysmorphism and pseudo-Pelger-Huët anomaly." (PMID 36044892, 2022). "To further explore the relevance of TMEM147 function during neurodevelopment, we studied its correlation with an established set of neurodevelopmental disorder (NDD)-associated genes." (PMID 36044892, 2022). "Here, we described a cohort of 23 affected individuals identified through an international collaboration who harbored bi-allelic disease-causing variants in TMEM147, thus offering a clinical profiling of a neurodevelopmental disorder caused by TMEM147 loss of function." (PMID 36044892, 2022). "Overall, these elements made TMEM147 an even stronger candidate for neurodevelopmental disorders." (PMID 36044892, 2022).
TMEM147 also shares sentences with these, for which no sentence is quoted: breast carcinoma (1 paper).